KRTAP13-4 (keratin associated protein 13-4)
Description:
In the hair cortex, hair keratin intermediate filaments are embedded in an interfilamentous matrix, consisting of hair keratin-associated proteins (KRTAP), which are essential for the formation of a rigid and resistant hair shaft through their extensive disulfide bond cross-linking with abundant cysteine residues of hair keratins. The matrix proteins include the high-sulfur and high-glycine-tyrosine keratins.
Synonyms: KAP13.4
Tractability: No criterion of Open Targets' tractability assessment is met for any kind of drug.
Gene: Protein-coding gene on chromosome 21 (30,430,220 to 30,431,026, forward strand). Ensembl gene ENSG00000186971.
Pathways (Reactome):
Developmental Biology: Keratinization
Gene Ontology:
Molecular function: protein binding
Cellular component: cytosol
Genetic constraint (gnomAD): Loss-of-function variants: 0 observed, 0.69 expected, observed/expected ratio (o/e) 0, 90% interval 0 to 1.8. That is too few expected variants to judge how well the gene tolerates losing a copy. Missense variants: 190 observed, 191.42 expected, observed/expected ratio (o/e) 0.99, 90% interval 0.88 to 1.12. Synonymous variants: 78 observed, 77.46 expected, observed/expected ratio (o/e) 1.01, 90% interval 0.84 to 1.22.
Homologues: Orthologues: macaque KRTAP13-4 (86% identical), rat Krtap13-1 (55% identical), mouse Krtap13-1 (54% identical), rabbit KRTAP13-4 (53% identical). Paralogues in human: KRTAP13-1 (77% identical), KRTAP13-2 (74% identical), KRTAP13-3 (63% identical), KRTAP15-1 (42% identical), KRTAP11-1 (32% identical), KRTAP26-1 (24% identical), KRTAP27-1 (24% identical), KRTAP25-1 (18% identical).